LPL (lipoprotein lipase)
Diseases named in the same sentence as LPL in open-access papers (continued):
Sharing a sentence is not in itself a finding about the gene and the disease.
tumor (continued). "Additionally, the upregulation of LPL, FATP2, and CPT1A, which are essential enzymes involved in FA metabolism, is directly correlated with tumor aggressiveness and lymph node metastases, making these viable biomarkers for PTC prognosis." (PMID 41041104, 2025). "Also, lipid metabolism studies have identified upregulation of LPL in PTC and a direct correlation between LPL expression and tumor size and lymph node metastasis." (PMID 40650680, 2025). "Under a high lactate microenvironment, lactylated-APOC2 is secreted via paracrine signaling into the tumor microenvironment (TME), where it binds to highly expressed lipoprotein lipase (LPL) to form the complex that enhances TG hydrolysis, thereby producing FFA for tumor metabolism." (PMID 40849305, 2025). "Interestingly, APOA1, FASN, FABP4, and LPL were oppositely dysregulated in liver and lung metastasis compared to the primary CRC tumour, whereas AGPAT1 was found to be significantly upregulated in lung metastasis." (PMID 35957902, 2022). "Vice versa, increasing LPL expression in HCC cells could reverse ZHX2-mediated cell proliferation inhibition, tumor growth in a xenograft mouse model, lipid metabolism, and tumor formation in mouse liver." (PMID 36232466, 2022). "Importantly, in vivo tests showed that LPL, FABP4, and CPT1-related inhibitors delayed tumor growth in STAM mice." (PMID 34803493, 2021). "The fact that basal-TNBC and CL-TNBC tumours had similar expression levels of MYC yet very different expression levels of CD36, LPL, PDK4 and FABP4 suggested that there are likely other factors, besides MYC, that direct activation of FAO and lipid metabolism in CL-TNBC." (PMID 31942031, 2020). "Importantly, LPL overexpression significantly reversed ZHX2-mediated inhibition of HCC cell proliferation, xenograft tumor growth, lipid deposition, and spontaneous liver tumor formation." (PMID 31740790, 2020). "The increased lipid accumulation in the heart, but not the tumour correlated with an increased tissue lipoprotein lipase level." (PMID 1764364, 1991). "It’s essential to consider that some of these effects might also be mediated by the lack of LPL inhibition within the activated vasculature of the tumor, as a pan-lipase inhibitor also reduced FA uptake in tumor-associated ECs." (PMID 38086791, 2023). "LPL is a crucial enzyme secreted by extracellular lipolysis and bound to the luminal surface of capillary endothelial cells, and it can potentially be supplied by tumor cells or by nonmalignant cells in the tumor microenvironment." (PMID 33364199, 2020). "More recently, ANGPTL4 was shown to bind and inhibit lipoprotein lipase, a function consistent with the cachexia induced by tumors, where a reduction of fatty acid incorporation into fat cells serves the energy needs of the tumor rather than the host." (PMID 15836779, 2005). "Additionally, as the cell experiments showed that the LPL inhibitor Ibrolipim can inhibit the proliferation and migration of LUAD A549, PC-9, and H975 cells, in this part, we will further explore the potential regulatory and tumor-influencing mechanisms of LPL in LUAD." (PMID 40427755, 2025). "Although we did not observe a significant difference in MYC (p = 0.08) or LPL (p = 0.11) expression between basal-TNBC and CL-TNBC, we did find that CL-TNBC tumours had significantly higher expression of CD36 (p < 0.0001) and PDGFRB (p < 0.0001)." (PMID 31942031, 2020).
cancer (69 papers, 2002 to 2026). A tumor composed of atypical neoplastic, often pleomorphic cells that invade other tissues. "While alipogene tiparvovec acts as an LPL agonist, its limited market presence and high cost have left the landscape of observational inquiries into its long-term cancer risk ambiguous." (PMID 38034491, 2023). "Recently, it has been reported that LPL gene deficiency, such as due to chromosome 8p22 loss, LPL gene polymorphism, and epigenetic changes in its promoter region gene, increases cancer risk, especially in the prostate." (PMID 22028972, 2012). "Several proteins positively associated with MVPA are inversely associated with disease risk (e.g., integrins, CLEC4A for cancer; LPL, LEP for T2D), while proteins negatively associated with MVPA are positively associated with disease risk (e.g., CD38, TGFA for CVD)." (PMID 41826625, 2026). "On the other hand, LPL gene deficiency increases cancer risk." (PMID 38086791, 2023). "Thus, cancer-susceptible genes mapped close to the LPL gene could be affected by LPL gene deletion, and exert combined effects in promoting carcinogenesis." (PMID 22028972, 2012). "Our analysis revealed a strong correlation between LPL expression and the presence of various immune cell types infiltrating multiple cancer types." (PMID 40427755, 2025). "In the setting of cancer cachexia, there is a significant reduction in the activity of lipoprotein lipase (LPL) in white adipose tissue (WAT)." (PMID 38334644, 2024). "It has been demonstrated that LPL downregulation and targeting by this drug is critical for cancer cell liposuction, which is crucial for providing the energy and molecules required for their fast growth and reproduction." (PMID 38791477, 2024). "The activities of fatty acid synthase (FAS) and LPL in adipose tissue of cancer patients were decreased." (PMID 37205195, 2023). "Further studies into the role of LPL in different cancers are necessary to understand the impact LPL has on tumorigenesis, and how it can be used as a potential target for therapy." (PMID 36652113, 2023). "Overexpression of FA biosynthetic genes including FAS, ACC, SREBP1, and LPL have been demonstrated in several cancer phenotypes." (PMID 38020549, 2023). "One potential mechanism of cancer cachexia is the hyperactivation and expression of LPL, which, if pharmaceutically reduced, modulates metabolic dysregulation, leading to solid tumor cachexia." (PMID 35992862, 2022). "Cancer cells utilize secreted lipases like lipoprotein lipase (LPL) to hydrolyze FA from triglycerides, and FA transporter proteins (FATP) like CD36 and SLC27 family members and FA-binding proteins (FABP) to facilitate uptake." (PMID 35732120, 2022). "Physiologic LPL expression is restricted to replicating hematopoietic cells, but LPL is also ectopically overexpressed in multiple transformed cancer cells." (PMID 35844504, 2022). "In particular, a reduction in the activity of LPL has been suggested to be a factor in cancer cachexia." (PMID 34621740, 2021). "For example, it has been reported that in addition to the markers of de novo synthesis (FASN) different cancer cells also express markers of lipolysis (lipoprotein lipase, LPL) and exogenous FA uptake (CD36)." (PMID 31138183, 2019). "Different types of cancer cells also express lipoprotein lipase (LPL), a lipolytic enzyme that is involved in the extracellular lipolysis of TG-rich lipoproteins (TGRL)." (PMID 31092908, 2019). "With regard to cancer cachexia, IL-6 decreased LPL activity in adipose tissue of mice and IL-1 directly modulates lipid metabolism by suppressing LPL activity." (PMID 29631586, 2018). "On the other hand, fat depletion associated with cancer is linked with a decrease uptake of VLDL and chylomicron triacylglycerol due to a decrease in lipoprotein lipase (LPL) activity." (PMID 26523094, 2015). "In this paper, we focus on the roles of LPL in cancer development and further discussed possible approaches to cancer prevention/therapy." (PMID 22028972, 2012).
cancer (continued). "Targeting LPL activity or expression levels for development of reagents against cancer seems particularly challenging, because LPL is expressed ubiquitously and plays essential roles in maintaining homeostasis in the body." (PMID 22028972, 2012). "Further investigations are warranted to clarify the importance of LPL and to accumulate evidence as to the worthiness as a target for cancer chemopreventive and chemotherapeutic agents." (PMID 22028972, 2012). "Lipolysis appears to be increased in cancer cachexia since in white fat lipoprotein lipase activity is decreased in tumour-bearing mice while hormone sensitive lipase mRNA is elevated in cancer patients with cachexia." (PMID 17047651, 2006). "A large number of animal studies have also shown that the activity of LPL is reduced in cancer." (PMID 37205195, 2023). "Sortilin regulates glucose metabolism and is upregulated by androgen, which also induces glucose uptake, while androgen deprivation leads to overexpression of syndecan-1 and increases its interactions with LPL and αVβ3 integrin to facilitate lipid metabolism and cancer aggression." (PMID 37596305, 2023). "The overexpression of fatty acid synthase (FASN) gives cancer cells a proliferative advantage; conversely, lipolysis, through the activation of lipoprotein lipase (LPL), could increase the availability of FAs to levels necessary for cancer cell proliferation." (PMID 36983080, 2023). "Specifically, LPL has mainly localized the periphery of cancer cells; CPT1 is mainly localized in the cytoplasm of cancer cells; FABP4 showed a certain degree of fuzzy staining in the cancer cells, which may be caused by its secretory status." (PMID 34803493, 2021). "Decreased activity of lipoprotein lipase has been observed in cancer cachexia." (PMID 34832866, 2021). "Moreover, focusing on histologic diagnosis, all types of NHL (FL, OR = 0.04, p < 0.001; LPL/WM, OR = 0.06, p = 0.008; MCL, OR = 0.12, p < 0.001; MZL, OR = 0.14, p = 0.004) were associated to lower second cancer rates than CLL patients." (PMID 33808164, 2021). "Conversely, cancer tissues with lower ZHX2 expression had higher LPL levels." (PMID 31740790, 2020). "Furthermore, it was reported that cancer cells can also acquire FAs from the circulation via lipoprotein lipolysis catalyzed by lipoprotein lipase (LPL)." (PMID 32226926, 2020). "Therefore, on this chromosome the LPL gene deletion moves the proximal cancer related genes in interrogation and their joint effect in the promotion of carcinogenesis are reported." (PMID 32847584, 2020). "Aberrant lipoprotein lipase expression has been reported to contribute to lipid dysregulation in several types of cancer and promote tumorigenesis by supplying cancer cells with lipid precursors, a high-energy fuel for cancer cell proliferation." (PMID 29350614, 2018). "Interestingly, the increased LPL activity in cancer tissue, compared with healthy lung tissue, predicts lower overall survival in non-small-cell lung cancer." (PMID 25866768, 2015). "Altered expression of LPL has been reported in many cancers." (PMID 25866768, 2015). "Numerous animal studies suggest reduced LPL activity in cancer." (PMID 25415607, 2014). "Moreover, LPL might be an excellent candidate target for cancer prevention or therapy in multiple cancer types." (PMID 38159259, 2023). "Since abnormal lipid metabolism is essential for the activity of cancer stem cell maintenance 26, 27, we assumed that the activation of the LPL/FABP4/CPT1 metabolic axis may be an important promoter to facilitate the progression of NASH to HCC through collaboration with oncogenic signals." (PMID 34803493, 2021). "Therefore, LPL promotes the proliferation of certain types of cancer cells." (PMID 34976793, 2021).
cancer (continued). "Decreased activity of fatty acid synthase and lipoprotein lipase was shown in adipose tissue of cancer patients and adipogenesis, a process essential to form mature adipocytes, is impaired in experimental models of cancer cachexia with reduced expression of adipogenic transcription factors." (PMID 30061533, 2018). "As both enzymes are molecular targets for cancer therapy, with specific inhibitors of FASN activity or by inducing LPL activity in non-cancer tissues by peroxisome proliferator-activated receptor γ agonists, PEMT may also be a promising diagnostic and therapeutic target." (PMID 24932311, 2014). "Thus, it might be important to develop selective LPL inducers or search for agents focusing on the aspect of “drug repositioning” to obtain the tools for investigating correlation between LPL and cancer." (PMID 22028972, 2012). "We further explored the expression patterns and clinical characteristics of LPL in LUAD and various other cancers." (PMID 40427755, 2025). "The Lipoprotein Lipase (LPL) gene stands out for its role in lipid metabolism and its potential involvement in providing fatty acids to cancer cells, thereby supporting their growth and survival." (PMID 38253993, 2024). "Among the transcription factors, SP1 was the only regulator that was common in both LPL and PCK1, and it mainly plays a role in transcriptional mis-regulation in cancer." (PMID 38791477, 2024). "GLUT1, FABPpm, MCT4 and SNAT1 genes were significantly overexpressed in carcinomas compared with controls, while expression of CD36/SR-B2, FATP1, FABP4, GLUT4, ASCT2 and LPL was decreased." (PMID 36012230, 2022). "Triglycerides present in circulating very low-density lipoproteins (VLDL) can be hydrolysed by lipoprotein lipase (LPL), which is highly expressed in several types of cancer." (PMID 34722305, 2021). "Conclusively, three key genes, LPL, FABP4 and CPT1, form the metabolic axis that regulates fatty acid production, transport and oxidization, which is essential for cancer cell activity." (PMID 34803493, 2021). "For instance, we found PALB2 in Cancer, JAK-STAT pathway in ‘Digestive System Disorder’ and LPL (Lipoprotein Lipase) in ‘Lipid or Lipoprotein Measurement’." (PMID 32678846, 2020). "In conclusion, increased PEMT expression in NSCLC tissues (relative to the adjacent non-cancer lung tissue) predicts shorter patient survival, independently of increased FASN or LPL activities in the same cancer tissues." (PMID 24932311, 2014). "PEMT predictive capacity in addition to LPL and FASN is explicable as FASN and LPL only supply the cancer tissue with long-chain fatty acids, which are then further used as constituents in phospholipid synthesis." (PMID 24932311, 2014). "Specifically, LPL is significantly negatively correlated with MSI in 10 cancer types including LGG, COAD, and COADREAD, suggesting that LPL may be involved in maintaining microsatellite stability or regulating related DNA repair mechanisms in certain cancers." (PMID 40427755, 2025). "The microsatellite instability (MSI) analysis results for LPL showed a significant negative correlation with MSI in 10 types of cancer including LGG, COAD, and COADREAD." (PMID 40427755, 2025). "Moreover, the lipases MAGL and LPL were over-expressed in UW479 and are well-known markers of aggressiveness in cancer." (PMID 29069732, 2017). "In addition, lipoprotein lipase hydrolyzes lipids from dietary sources and subsequently CD36 takes up the fatty acids, and increased expression of lipoprotein lipase is found in a variety of cancers." (PMID 40028336, 2025).
cancer (continued). "However, hypoxia-mediated regulation of LPL-regulated extracellular lipolysis in cancer cells has not been investigated in detail." (PMID 31092908, 2019). "This study hypothesized that circulating lipoproteins could carry cholesterol into cells to provide cellular needs; the gate for lipoprotein entrance (lipoprotein receptors) and the enzyme to release lipids from lipoproteins (Lipoprotein Lipase; LPL) could be a cancer facilitator as well." (PMID 27893427, 2017). "Notably, LPL exhibited strong positive correlations with mast cells, dendritic cells, and macrophages across LUAD and other cancer types while showing negative correlations with immunosuppressive cells such as NK cells and Th2 cells." (PMID 40427755, 2025).
cardiovascular disease (67 papers, 2009 to 2026). "Nevertheless, we cannot exclude the long-term risk of cardiovascular disease in individuals with LPL deficiency who maintain TG levels between 10 and 20 mmol/L." (PMID 37630727, 2023). "The association of LPL deficiency with an increased risk of cardiovascular disease is still controversial." (PMID 37630727, 2023). "The PvuII (rs285) LPL polymorphism, which is a C to T transition in intron 6 of the LPL gene, is associated with the risk of cardiovascular disease (CVD)." (PMID 35456470, 2022). "Apo CIII inhibits LPL and dysregulation of this protein is associated to cardiovascular disease (CVD)." (PMID 28974732, 2017). "Recent data suggest that the PvuII polymorphisms of LPL play critical roles in the development of metabolic and cardiovascular disease." (PMID 28814963, 2017). "Alterations in lipoprotein lipase activity may affect the lipid profile and consequently the risk of cardiovascular disease, including complications of pre-eclampsia." (PMID 41234028, 2025). "This study examined the association between the rs320 polymorphism, related to lipoprotein lipase levels, and cardiovascular disease risk factors, as well as potential interactions between this polymorphism and prevalent dietary patterns on cardiometabolic risk factors." (PMID 41372238, 2025). "LpL gene polymorphism rs328 has been associated with a reduced risk for cardiovascular disease." (PMID 38507115, 2024). "The lipoprotein lipase has also been identified as a risk factor for cardiovascular disease, suggesting that the related study of apolipophorin may be important." (PMID 34260548, 2021). "LPL hydrolyzes lipoproteins from chylomicrons and very low-density lipoproteins to create more free triglycerides in serum; notably, high triglyceride levels are implicated in the development of cardiovascular disease." (PMID 28900399, 2017). "Furthermore, APOC-III is an inhibitor of LPL activation and it is considered as a risk factor for cardiovascular diseases." (PMID 26616161, 2015). "One locus, LPL, has also been robustly associated with risk for cardiovascular disease." (PMID 25147553, 2014). "LPL, apoE, and PPARα are known as important components of lipid metabolism with roles in the homeostasis of different lipoprotein fractions and their transport, and the polymorphisms of these genes have been associated with cardiovascular diseases." (PMID 25242866, 2014). "Therefore, our data suggest that enhancing LPL activity may also ameliorate glucose metabolism while further reducing the risk of cardiovascular disease in people taking LDL-C–lowering therapy." (PMID 30326043, 2018). "This relationship between lipoprotein lipase, triglycerides and HDL is essential for maintaining a healthy lipid profile and reducing the risk of cardiovascular disease." (PMID 40047002, 2025). "LPL mediation shows promise as a potential therapeutic that would ultimately drive shifts in lipid metabolism across neurodegenerative and cardiovascular diseases." (PMID 41332650, 2025). "It would be more attractive to see how environmental factors such as diet and exercise influence epigenetic LPL regulation to provide new insights into developing personalized treatments for T2D and cardiovascular disease." (PMID 41373652, 2025). "Elevated HDL cholesterol levels correlate with a lower risk of cardiovascular disease, and HIIT has been shown to promote beneficial changes in lipid metabolism by increasing lipoprotein lipase activity and enhancing lipid transport." (PMID 40904707, 2025).